ENSG00000290642 (novel transcript)
Gene: Long non-coding RNA gene on chromosome 14 (23,293,852 to 23,295,726, forward strand). Ensembl gene ENSG00000290642.
Gene Ontology:
Biological process: SRP-dependent cotranslational protein targeting to membrane, signal sequence recognition
Cellular component: signal recognition particle, endoplasmic reticulum targeting